TNF (tumor necrosis factor)
Diseases named in the same sentence as TNF in open-access papers (continued):
Sharing a sentence is not in itself a finding about the gene and the disease.
Obesity (continued). "Given its ability to decrease the tyrosine kinase activity of the insulin receptor, TNF-α is an important mediator of IR in obesity and type 2 diabetes mellitus." (PMID 35282448, 2022). "Under inflammatory conditions, such as obesity and aging, the increase in IL-6 levels is accompanied by higher levels of TNF-α and its receptors, which are responsible for inducing pro-apoptotic responses." (PMID 36139762, 2022). "Obesity is also related to increases in pro-inflammatory cytokines, such as interleukin-6 (IL-6) and tumor necrosis factor-alpha (TNF-α)." (PMID 35571885, 2022). "It is suspected that TNF-α in obesity comes from adipose tissue macrophages and, in psoriasis, from activated T cells." (PMID 35330186, 2022). "Evidence suggests that the elevations in pro-inflammatory cytokines observed in obesity, including interleukin 6 (IL-6), tumor necrosis factor-alpha (TNF-α), monocyte chemoattractant protein-1 (MCP-1), and serum amyloid, can be reduced via weight loss." (PMID 35350649, 2022). "ω3-Polyunsaturated fatty acids exert anti-inflammatory effects and can reduce the levels of inflammatory cytokines, such as IL-1, IL-6, and TNF-α, and mitigate adipose tissue inflammation in animal models of obesity." (PMID 35887932, 2022). "The cytokines produced by the subset T helper 1 cells, are responsible for pro-inflammatory cytokine release of INF-γ, IL-2 and TNF-α, which are increased in obesity." (PMID 36292751, 2022). "Increases in serum IL-6, TNF-α, MCP-1, and TBARS, and reduction in serum TAC was statistically associated with the history of dyslipidemia, diabetes, and obesity." (PMID 36032093, 2022). "In rodents, a high-fat diet significantly increases serum TNFα in both obese and obesity-resistant rats, and neonatal overfeeding markedly increases mouse serum TNFα." (PMID 35884707, 2022). "ATMs in obesity are polarized towards a proinflammatory M1 phenotype, elaborating proinflammatory cytokines such as TNF-α." (PMID 36726470, 2022). "The expansion of adipose tissue in obesity leads to increased macrophage infiltration and inflammation with an increased production of proinflammatory cytokines such as TNF-a and IL-6." (PMID 36547041, 2022). "Tumor necrosis factor alpha (TNF-alpha)is a pro-inflammatory adipokine associated with insulin resistance and βcell failure in T2DM and obesity." (PMID 39077619, 2022). "Simultaneously, peroxisome proliferator-activated receptor-γ (PPAR-γ) and TNF-α were downregulated, which ensured enhanced anti-obesity effects." (PMID 35893900, 2022). "Nonetheless, future studies are warranted to investigate alternative mechanisms linking obesity and poor PF, in particular the mediating roles of IL-6 and TNF-α." (PMID 35301057, 2022). "In obesity, the endocrine function of adipocytes is changed, with decreased adiponectin and increased levels of leptin, resistin, IL-6, and tumor necrosis factor (TNF)." (PMID 36299943, 2022). "Obesity and inflammatory markers such as tumor necrosis factor-α and interleukin-6 were considered in relation to TyG; these factors can increase the difficulty of surgery and the possibility of blood transfusion." (PMID 35480095, 2022). "In obesity conditions, high TG levels stimulate many inflammatory markers, such as tumor necrosis factor-α (TNF-α) and reactive oxygen species (ROS), which induce mitochondrial damage and decrease mitochondrial membrane potential (Ψm)." (PMID 35209178, 2022). "Obesity and OSA are conditions linked to higher levels of inflammatory cytokines in nasal tissue, such as C-reactive protein, tumor necrosis factor alpha, interleukins, and granulocyte-macrophage colony-stimulating factor." (PMID 32782124, 2022). "Obesity, which is closely associated to T2DM, leads to high proinflammatory cytokines (IL1, IL6, IL8, TNF-alpha) and adipokines which further hinder the subjects’ immunity." (PMID 36360537, 2022).
Obesity (continued). "SBH and Sim inhibited the inflammation accompanied by obesity via decreasing inflammatory cytokine interleukin (IL)-1β, tumor necrosis factor α (TNFα), and monocyte chemoattractant protein 1 (MCP1)." (PMID 35889886, 2022). "The evidence on the relationship of obesity and anti-TNF combination therapy is limited, however, a systematic review and meta-analysis explored differences between pre and post- anti-TNF therapy on patients’ weight." (PMID 36687448, 2022). "Weight gain and obesity often result in the increased secretion of inflammatory factors and chemokines, including tumor necrosis factor alpha (TNFα), interleukin 6 (IL6), and monocyte chemoattractant protein-1 (MCP-1)." (PMID 36501080, 2022). "The most important finding is that TNF-α concentrations were similar in patients with normal body weight, overweight and obesity." (PMID 36428528, 2022). "The obesity-induced pro-inflammatory shift of immune cells is a condition that favors the release of pro-inflammatory cytokines (TNF and IFNγ) and goes hand in hand with a reduction in the release of protective cytokines (IL-10 and IL-22) and adipokine." (PMID 36648872, 2022). "TNF-α is a major protein related to obesity that plays an important role in regulating fat metabolism; it is positively correlated with obesity and inhibits intracellular signaling from the insulin receptor, leading to diabetes." (PMID 35409375, 2022). "A reduction in levels of obesity seems to produce a reduction on TNF-α, which lead to a decline in leptin and an increase in adiponectin and insulin sensitivity." (PMID 35529460, 2022). "Most patients with obesity exhibit increased circulating levels of inflammatory markers such as IL-6, IL-1, TNF and MCP1." (PMID 35842665, 2022). "Elevated levels of Erysipelotrichaceae have been linked to human obesity and have been correlated with elevated levels of Tumor Necrosis Factor-alpha (TNF-α), a pro-inflammatory cytokine involved in obesity-linked insulin resistance." (PMID 35413875, 2022). "While IL‐10, an anti‐inflammatory cytokine, is usually lower in patients with obesity, TNF‐α, a proinflammatory cytokine, shows the opposite trend." (PMID 35837843, 2022). "They demonstrated the role of TNF- α in obesity, particularly in insulin resistance and diabetes (Hotamisligil, Shargill & Spiegelman, 1993; Alzamil, 2020)." (PMID 36213511, 2022). "In MAFLD and obesity, adipocytes and kupffer cells have been shown to increase the secretion of proinflammatory cytokines such as tumor necrosis factor-alpha (TNF-α)." (PMID 36531832, 2022). "Further studies found that TNF-α is an adipose tissue-derived proinflammatory cytokine that is involved in obesity-induced insulin resistance." (PMID 36230963, 2022). "We found that Sirt6loxp/loxp;Cre− mice had significantly higher levels of secreted TNFα in the peritoneal cavity than Sirt6loxp/loxp;Cre + mice, confirming that SIRT6 deletion in macrophages ameliorates TNFα secretion in vivo during obesity." (PMID 35150745, 2022). "Obesity triggers inflammation marked by the secretion of low-grade inflammatory cytokines including interleukin-6, C-reactive protein, and tumor necrosis factor-α, leading to a condition known as “meta-inflammation”." (PMID 35740977, 2022). "IL-6 and TNFα are cytokines that are widely used as indicators of the pro-inflammatory state that characterises obesity and contribute to insulin resistance." (PMID 35883817, 2022). "Many proinflammatory cytokines such as TNFα and IL-6 are expressed under the induction of obesity or LPS." (PMID 36430282, 2022). "This is in contrast to what is typically seen in individuals with obesity, who tend to have higher circulating TNF‐α and IL‐6 that subsequently decrease following interventions that combine diet and exercise that lead to reductions in fat mass." (PMID 35312183, 2022). "HFD-induced obesity leads to elevated levels of many inflammatory cytokines in eVAT, notably TNFα, IFNγ, and IFNα." (PMID 36337732, 2022).
Obesity (continued). "On the other hand, obesity is characterized by a pro-inflammatory state with increased outflow of inflammatory cytokines (i.e., IL-6 and tumor necrosis factor-alpha)." (PMID 35334962, 2022). "TNF-α is the first cytokine identified to link inflammation and obesity, which is highly expressed in obese people and obese murine models." (PMID 36139760, 2022). "An increased level of tumor necrosis factor alpha (TNF-α) initiates the link between obesity and inflammation." (PMID 35883424, 2022). "Although FSTL1 expression is low in adipocytes and macrophages, it can be induced by inflammatory stimuli such as TNF-α and LPS, suggesting its potential role in mediating obesity-induced inflammation." (PMID 35909571, 2022). "Regarding the effect of different training modalities on TNF-α levels in adolescents with obesity, there was homogeneity between these studies (I2 = 45%, p = 0.11)." (PMID 36293806, 2022). "Patients with obesity produce higher levels of cytokines such as IL-6, C-reactive protein and TNF-α than normoweight individuals." (PMID 35955431, 2022). "It is worth to note that TNF-α also contributes to insulin resistance in overall obesity, altering the metabolic landscape." (PMID 35164764, 2022). "Muscle atrophy is induced by inflammatory cytokines such as TNF-α and IL-6 secreted from fat cells enlarged by obesity." (PMID 35711555, 2022). "M1 macrophages are considered key mediators of obesity-induced IR as they increase the expression of pro-inflammatory cytokines, such as tumor necrosis factor-α (TNF-α) and interleukin (IL)-6, and the levels of reactive oxygen and nitrogen intermediates." (PMID 36297306, 2022). "We also measured serum concentrations of tumor necrosis factor -α (TNFα), which has postulated roles in obesity and insulin action." (PMID 35198905, 2022). "This is also demonstrated by decreased IFN-γ and TNFα production in stimulated polyclonal T cells from individuals with obesity." (PMID 36466818, 2022). "Obesity is a common comorbidity of RA patients, and it also reduces the efficacy of drugs working against TNF-α, but losing body weight improves the success of treatment with these drugs." (PMID 35267958, 2022). "This research aimed to explore the relationship between tumor necrosis factor-α (TNF-α), Lactobacillus acidophilus (L. acidophilus), Lactobacillus gasseri (L. gasseri), obesity, and early childhood caries." (PMID 35631100, 2022). "Due to obesity and secretion of selected cytokines (IL-6 and TNF- α), the anti-inflammatory phenotype of macrophages changes into a proinflammatory phenotype." (PMID 36555323, 2022). "In conclusion, laboratory tests showed that TNF-α concentrations were similar in patients with a normal body weight, overweight and obesity, whereas sTNFr1 levels were higher in normal-weight patients." (PMID 36428528, 2022). "During the progression from normal weight to obesity and on to overt diabetes, TNF-α contribute to the occurrence and development of β cell dysfunction and T2MD." (PMID 35198097, 2022). "It is imperative to underscore that most studies involving obesity assess TNF-α in serum, in the adult population or adolescents, demonstrating that obesity was allied to increased levels of TNF-α in the bloodstream." (PMID 35631100, 2022). "In contrast, the TNFα inhibitor etanercept was shown to lower fasting glucose in patients with obesity over a 6-month period." (PMID 35557517, 2022). "The effect of obesity on the equine uterus has not been well defined, although gene expression in the endometrium was altered even after short-term obesity, showing a pro-inflammatory profile with increased expression of TNFα and IL1β." (PMID 35563743, 2022). "An increase in M1 macrophages, which form a structure around adipocytes and release pro-inflammatory mediators such as IL-1, IL-6, IL-12, TNF-α, and chemokines, is part of the alteration in immune cell profile that is characteristic of obesity." (PMID 35740977, 2022).
Obesity (continued). "In cases of obesity, the adipocytes secrete pro-inflammatory cytokines such as TNF-α and IL-6, which stimulate the liver’s production of CRP, altering the hosts’ immune response, and increasing their susceptibility to bacterial infections." (PMID 36661547, 2022). "Studies have shown that obesity promotes the secretion of pro-inflammatory cytokines from adipocytes and macrophages, including TNF-α, IL-1β, and IL-6." (PMID 36139760, 2022). "Studies have demonstrated that subjects with obesity have elevated circulating pro-inflammatory cytokines, including tumor necrosis factor-α (TNF-α), interleukin-6 (IL-6) and C-reactive protein (CRP)." (PMID 35252310, 2022). "Interleukin-6 (IL-6) and tumor necrosis factor (TNF), two pro-inflammatory indicators, rise in response to infection, tissue injury, and states of active stress like obesity." (PMID 36330087, 2022). "High fat diet caused metabolic, chronic, low-grade inflammation in the body because it induced obesity and the release of adipokines and inflammatory factors (For example, IL-1, IL-6, and TNF-α)." (PMID 37431015, 2022). "We found that SIRT6 downregulation in macrophages after the onset of obesity, decreased systemic inflammation and TNFα secretion, as well as improved glucose management." (PMID 35150745, 2022). "The AZGP1 gene is involved in the TNF-alpha and IL-1 beta (IL-1b) pathways, which are involved with the occurrence of dyslipidemia and inflammation in adipocytes, leading to the development of obesity and type 2 diabetes diseases." (PMID 35804531, 2022). "Over 15 years ago, it was stated that IL-1β was released by human adipocytes and was regulated by TNFα in obesity." (PMID 35139823, 2022). "Endometrial cells stimulated with TNFα (as obesity-marker) were also used to partially emulate an obesity environment." (PMID 35409282, 2022). "Obesity generates a proinflammatory state through the secretion of inflammatory mediators including tumor necrosis factor (TNF)-a and C-reactive protein (CRP)." (PMID 36687448, 2022). "Increased adiposity or body weight gain were reported as side effects in a study treating obesity or autoimmune diseases with anti-TNFα antibodies." (PMID 35557517, 2022). "TNFα is a crucial cytokine in neuroinflammation secondary to obesity, even critical in glucose metabolism by attenuating insulin signaling pathways and increasing levels of IL6, activating a neuroinflammatory state." (PMID 35422689, 2022). "Inversely, macrophage-derived TNFα during obesity inhibits Adiponectin levels in AT, whereas in lean state, Adiponectin inhibits macrophage “foam cell” formation as well as endothelial cell activation and monocyte recruitment (Sikaris, 2004)." (PMID 35543703, 2022). "Adipose tissue produces increased levels of inflammatory markers, including TNF-α and IL-6 in dietary manipulated obesity models." (PMID 36056976, 2022). "SAA is a nonspecific acute phase protein mainly produced by the cytokines IL-1β, IL-6, and TNF-α in liver cells, which increase in chronic inflammatory processes, as in diabetes and obesity." (PMID 35047039, 2022). "Several recent studies demonstrated that the levels of inflammatory factors, such as TNF-α and IL-6, in patients with obesity and type 2 diabetes mellitus, are significantly higher than those in the control group and positively correlated with serum ASP." (PMID 35381008, 2022). "Increased free fatty acids levels determined by obesity and TNF-α induce inflammatory cytokines and chemokines, thus establishing a vicious cycle." (PMID 35885044, 2022). "Obesity, as a chronic inflammatory condition, has been well reported to maintain increased systemic interleukin (IL)-2, IL-4, IL-6, TNFα, IFNγ, and GM-CSF levels in a manner modulated by physical activity." (PMID 36143948, 2022). "The levels of inflammatory cytokines related to the development of obesity, such as TNFα, IL-6, and MCP-1, were higher in the adipose tissues of Reg4 KO mice than in those of the control mice." (PMID 35074011, 2022).
Obesity (continued). "Studies have shown that the occurrence of various obesity-related chronic diseases, such as type 2 diabetes and atherosclerosis, are inseparable from inflammatory factors such as IL-6 and TNF-α." (PMID 35757707, 2022). "The obesity- and inflammation-related gene (IL-6, TNF-α, IGF-1, leptin, AP2/FABP4, AMPK-α2, β3AR, and PPAR-γ) expressions in the liver and epididymal adipose tissue were reduced in the PHPB-treated group." (PMID 35386305, 2022). "Obesity is linked to elevated levels of inflammatory serum markers such as C-reactive protein (CRP), interleukin-6 (IL-6), and tumor necrosis factor alpha (TNFa)." (PMID 35679338, 2022). "Our findings extend the role of SIRT6 in the regulation of TNFα-mediated inflammation to chronic inflammation and glucose management during obesity." (PMID 35150745, 2022). "Obesity can induce gastritis mediated by tumor necrosis factor-α (TNF-α), interleukin-6 (IL-6), and chemoattractive protein-1 (MCP-1)." (PMID 35954495, 2022). "Increased TNF with obesity impairs insulin signaling and contributes to insulin resistance and diabetes." (PMID 37990728, 2022). "TNF-α is related to the development of obesity-related insulin resistance, whereas IL-6 promotes lipolysis." (PMID 36304965, 2022). "In the context of obesity, a broad range of human intervention dietary studies have investigated the changes on the blood levels of TNF-α in connection with body weight changes." (PMID 36010524, 2022). "In the PANTS study, we showed that obesity, cigarette smoking, higher baseline markers of disease activity, anti‐TNF monotherapy and the development of antidrug antibodies are associated with low drug levels and anti‐TNF treatment failure." (PMID 35768996, 2022). "PPARγ agonists have been shown to reduce blood glucose and insulin resistance, by comparing the effect of TNF-α in adipocytes, with potential therapeutic targets for obesity, dyslipidemia and diabetes." (PMID 35330131, 2022). "Special consideration was given to the involvement of TNF-α, IL-6, and NF-κB, among others, in both the obesity-provoked inflammation and the development of DM." (PMID 36457603, 2022). "Obesity usually leads to IR, Some studies have shown that altered secretion of cytokines in obesity such as TNF-α, IL-6, and leptin induce IR in obesity, while adiponectin stimulates insulin sensitivity." (PMID 36451420, 2022). "The therapeutic effect of adipose-derived MSCs on obesity-related complications (e.g., NAFLD, CVD, and renal diseases) in animal models of diet-induced obesity derives from the attenuation of inflammatory cytokines such as TNF-α and IL-6." (PMID 35895169, 2022). "The pro-inflammatory cytokine TNF-α was another crucial factor for the activation of caspase-1-dependent hepatocyte pyroptosis in patients with obesity and NASH." (PMID 36324154, 2022). "Pro-inflammatory cytokines such as tumor necrosis-alpha (TNF-α), interleukin-1 (IL-1), and interleukin-6 (IL-6), which are increased in response to obesity, induce insulin resistance at a molecular level by modulating the insulin signaling pathway." (PMID 35883605, 2022). "Obesity directly drives adipocyte cells towards inflammatory phenotypes, releasing pro-inflammatory cytokines, such as leptin, IL-6, IL-10, TNF-α." (PMID 35069893, 2022). "Studies using a rodent model of neuropathic pain and obesity demonstrated that tDCS can prevent increases in IL-1β, TNF-α and IL-10 triggered by chronic constriction injury in a neuropathic pain model or hypercaloric diet in a model for obesity." (PMID 36620466, 2022). "Intriguingly, TNF-α also relates to metabolic dysfunctions such as anorexia and cachexia which share with obesity overlapping inflammatory mediators and IR but opposite relationship with fat mass." (PMID 36010524, 2022). "High serum levels of adiponectin, TNF-α, and MCP-1 are considered as major causes of obesity-associated chronic inflammation in CON ob/ob mice." (PMID 35409375, 2022).